RETN (resistin)
Diseases named in the same sentence as RETN in open-access papers (continued):
Sharing a sentence is not in itself a finding about the gene and the disease.
Insulin resistance (continued). "In addition, the expression of resistin was higher in the plasma of HFD-fed mice and its inhibition improved HFD-induced hepatic insulin resistance." (PMID 28036389, 2016). "What became apparent in the case of resistin was that observations of a potent effect on insulin resistance in rodents were not successfully reproduced in humans." (PMID 26097512, 2015). "We conclude that serum adiponectin concentrations are lower in Asian as compared to Italian and American children, and that adiponectin but not resistin contributes to differences in markers for insulin resistance in children from different populations." (PMID 25904939, 2015). "We have previously shown that plasma resistin is related to adiposity but not insulin resistance measured by glucose clamp in healthy humans." (PMID 26110385, 2015). "In our study we observed a significant negative correlation between plasma resistin levels and energy balance and plasma resistin levels and dry matter between WPP1 and WPP2.After calving, hypoleptinemia may contribute to peripheral insulin resistance." (PMID 24675707, 2014). "The possible effect of resistin on the development of insulin resistance has been evaluated; however, the results are not clear yet." (PMID 24741627, 2014). "Studies have reported strong evidence that suggests YKL-40, α-HB, soluble CD36, leptin, resistin, IL-18, RBP4, and chemerin could be new biomarkers for the pathogenesis of insulin resistance and endothelial dysfunction in T2DM patients." (PMID 24282409, 2013). "Assuming this data it seems that resistin alone is not a trigger of insulin resistance in obese OSA patients." (PMID 23497617, 2013). "The other biomarkers, indicative of insulin resistance and oxidative stress also turned to play no role on resistin plasma levels." (PMID 23497617, 2013). "Resistin (ADSF/FIZZ3/XCP1), 10 kDa polypeptide with 114 amino acids in rodents, is identified as an inducer of pulmonary inflammation and insulin resistance." (PMID 23781214, 2013). "Resistin is expressed at very low levels in human adipocytes and does not seem to correlate with insulin resistance." (PMID 20360975, 2010). "RBP4 serum levels did not correlate with adiponectin, resistin or ghrelin serum concentrations, nor did adiponectin, resistin or ghrelin correlate with insulin resistance (data not shown)." (PMID 20932285, 2010). "In obese PCOS, the altered inflammatory milieu—driven by TNF-α, IL-6, and resistin—can induce the release of EVs enriched with pro-inflammatory microRNAs that disrupt IRS phosphorylation, impede GLUT4 translocation, and modify FOXO1-mediated transcription, thereby exacerbating insulin resistance." (PMID 41010046, 2025). "In addition, in obesity, pro-inflammatory mediators (leptin, resistin, IL-6, and TNF-α) may promote adipose tissue dysregulation and systemic insulin resistance." (PMID 39065815, 2024). "However, due to the small size of the Study and Control Groups the role of diet in the treatment of insulin resistance in PCOS cannot be unequivocally stated; the same is true of the role of lifestyle intervention in modulating adiponectin, leptin and resistin concentrations." (PMID 37432289, 2023). "Insulin resistance in humans by resistin is not clear as in rodents." (PMID 37014444, 2023). "Resistin is released as part of the adipose dysfunction to produce higher insulin resistance; however, this study was not guided to measure adipocytokines nor the molecular expression of glucose transporters, so resistin and GLUT-4 translocation were not assessed." (PMID 36233611, 2022). "Thus, the potential local effect of IMAT‐derived resistin on skeletal muscle function highlights the negative consequences of IMAT accumulation on skeletal muscle that can contribute to the development of insulin resistance." (PMID 35980018, 2022).
Insulin resistance (continued). "In addition, previous studies found that resistin was weakly correlated with other inflammatory molecules such as TNF-α, IL-6, insulin, and insulin resistance measured by homeostasis model assessment-insulin resistance (HOMA-IR)." (PMID 36428592, 2022). "Conversely, insulin resistance was not correlated to resistin." (PMID 34996484, 2022). "These include adiponectin, resistin, interleukin-6 (IL-6), tumor necrosis factor-α (TNF-α), and monocytic chemotactic protein (MCP-1) that influence not only body weight homeostasis but also insulin resistance, diabetes, lipid levels, inflammation, and atherosclerosis development." (PMID 33865458, 2021). "In addition, non-esterified fatty acids (NEEAs) and resistin secreted by adipose tissue were directly related to insulin resistance." (PMID 33514431, 2021). "In contrast, in KK-Ay mice fed high-fat diet (a model for T2D possessing insulin resistance), dietary supplementation with EA (0.1%) for 68 days did not affect serum glucose or insulin, although it reduced serum resistin and improved serum lipid profile and hepatic steatosis." (PMID 33287432, 2020). "However, our previous study demonstrated that serum resistin levels were positively correlated with serum lipids and not with insulin resistance in first-degree relatives of patients with T2DM." (PMID 33336025, 2020). "Some studies have suggested that resistin might not play a main role in insulin resistance or energy metabolism in humans." (PMID 31690939, 2020). "The mechanisms by which resistin can induce insulin resistance are not fully elucidated in humans." (PMID 33227979, 2020). "Resistin in our study was decreased in obese mice, indicated that insulin resistance may not evoked by resistin." (PMID 31788033, 2019). "Few studies concentrating on the correlation between resistin and insulin resistance without reporting the correlation coefficient may have introduced bias." (PMID 31803062, 2019). "So far, the mechanisms of insulin-resistance related effects of resistin are not clear in humans." (PMID 31803062, 2019). "Furthermore, VCE-004.8 could also lower resistin levels in HFD mice, further contributing to the decrease of insulin resistance." (PMID 30382123, 2018). "Although human resistin is mainly produced by the macrophages rather than the adipocytes, experimental studies suggest that human resistin exacerbates adipose tissue inflammation and contributes to insulin resistance." (PMID 30416448, 2018). "Although, we hypothesized that older US and Italian children would have higher insulin resistance, lower adiponectin, and higher resistin compared to Japanese and Thai children, our data did not confirm our initial hypothesis." (PMID 25904939, 2015). "Overall it appears that resistin may mediate insulin resistance during pregnancy, but it is unlikely to have a central role in glucose homeostasis and development of GDM." (PMID 26110385, 2015). "However, short-term dexamethasone administration, which enhanced insulin resistance, did not alter circulating resistin levels in obese subjects." (PMID 25129652, 2015). "Levels of circulating resistin are increased in obese mice and correlated with insulin resistance, whereas a lack of resistin protects mice from diet-induced hyperglycemia by increasing the activity of AMPK and decreasing the expression of gluconeogenic enzymes in the liver." (PMID 24733068, 2014). "Unlike mouse resistin, human resistin is exclusively expressed in mononuclear cells including macrophages, and macrophage-derived human resistin exacerbates adipose tissue inflammation and insulin resistance in mice." (PMID 24733068, 2014). "The proinflammatory effects of resistin were attributed to its ability to activate NF-kB signaling pathway and subsequently increase the production of proinflammatory cytokines including TNF-α and IL-6, both of which can impair insulin signaling pathways and lead to insulin resistance." (PMID 23772224, 2013).
Insulin resistance (continued). "Finally, resistin has been demonstrated to stimulate the secretion of several inflammatory factors (e.g., TNF-α, IL-6, IL-8, and MCP-1) known to play a role in the induction of insulin resistance." (PMID 24455420, 2013). "This shows that resistin alone could not be an indicator of insulin resistance in OSA patients, at least not in extremely obese one." (PMID 23497617, 2013). "In addition, resistin can activate SOCS-3 protein, which can lead to insulin resistance." (PMID 23772224, 2013). "However, the role of resistin in the development of insulin resistance in humans is not as clear as in rodents." (PMID 24455420, 2013). "Interestingly, NT-proCNP in critically ill patients was indeed correlated with endogenous insulin levels (C-peptide) as well as serum resistin and retinol-binding protein 4, two mediators of insulin resistance (data not shown)." (PMID 21281508, 2011). "However, later studies in patients with renal disease found a correlation between elevated blood resistin levels and inflammation or decreased glomerular filtration rate but not with insulin resistance." (PMID 21048961, 2010). "• TNFα, and resistin do not predict stress induced insulin resistance in our model." (PMID 19087258, 2008). "This prompted the hypothesis of resistin being a prominent mediator of inflammatory insulin resistance in humans, which we could not confirm in this study." (PMID 19087258, 2008). "Overexpression of resistin increased the levels of three proinflammatory cytokines, tumor necrosis factor alpha (TNFα), interleukin 6 (IL-6) and monocyte chemoattractant protein-1 (MCP-1), which play important roles for insulin resistance, glucose and lipid metabolisms during adipogenesis." (PMID 16854242, 2006). "However, so far, the mechanisms by which insulin resistance may modulate resistin in humans are not clear." (PMID 35011183, 2021). "However, the overall effect of resistin was not significant in people with low resistin levels, several other factors may dominate insulin resistance like free fatty acids, hyperosmotic stress, and TNF-α." (PMID 31803062, 2019). "However, the link between resistin and insulin resistance in humans has not been proven." (PMID 31623226, 2019). "A recent in vitro study found that the expressions of resistin (RETN), TNF-α, and C-C motif chemokine ligand 2 (CCL2) of mouse and human pre-adipocytes/adipocytes, were increased by IHR via down-regulation of miR-452, which may play a protective role in the development of insulin resistance." (PMID 31208080, 2019). "In conclusion, we found that circulating levels of novel adipose tissue-derived inflammatory factors, including resistin, vaspin and visfatin, may change according to the severity of atherosclerosis in elderly patients of T2DM, and these factors were correlated with the degree of insulin resistance." (PMID 29848323, 2018). "The observed reduction of insulin concentration and insulin resistance by the Okinawa-based Nordic diet seem to be interconnected with lower levels of adipokines, although the close relation between resistin and insulin resistance found in other studies could not be confirmed in the present study." (PMID 29599686, 2018). "Emerging evidence has shown that resistin, a peptide hormone classified as an adipokine although in humans it is mainly produced by mononuclear cells and macrophages, is important in regulating insulin resistance, diabetes, inflammatory processes, immunity, and bone metabolism." (PMID 25784935, 2015). "Further studies have shown that in humans the majority of resistin is derived from macrophages (nonfat stroma fraction of adipose tissue) and, to a lesser extent, from adipocytes, which explain various results in relation to insulin resistance in mouse and human." (PMID 21912448, 2011).
Insulin resistance (continued). "The negative correlation between serum resistin and adiponectin levels may also suggest that, resistin could be a marker for TNF-α which has been shown to be associated with chronic inflammation and insulin resistance." (PMID 16669997, 2006). "Serum but not urine resistin has been correlated with SLE disease activity, insulin resistance, and renal dysfunction in LN." (PMID 39201667, 2024). "Although obese adolescents had clear evidence of insulin resistance, only CRP, fibrinogen and leptin were elevated; there were no group differences in pro- or anti-inflammatory cytokines nor adiponectin and resistin." (PMID 22682228, 2012). "In OSA patients with BMI>40 resistin plasma levels correlated neither to the clinical parameters (BMI, IRI, HOMA-I, HbA1C, AHI, desaturation index), nor to the biomarkers of oxidative stress and insulin resistance." (PMID 23497617, 2013). "In addition, other surrogate indicators of insulin resistance were not affected by Pioglitazone treatment on day-14, including fasting serum insulin; C-peptide; SHBG; resistin; and adiponectin." (PMID 22412837, 2012).
diabetes (258 papers, 2004 to 2026). "RETN was initially identified in mouse adipose cells and has been associated with the development of diabetes." (PMID 40599778, 2025). "Cluster 1 scores were positively associated with peak VO2 and C[a‐v]O2 and negatively associated with age and resistin (p < 0.01 for all), with weaker correlations with diabetes and leptin." (PMID 41351269, 2025). "Broadly, resistin contributes to the perpetuation of dysglycemia characteristic of diabetes, promoting pro-inflammatory states and causing endothelial dysfunction." (PMID 40283140, 2025). "An increased risk of developing diabetes is also associated with increased leptin secretion, resistin and decreased adiponectin secretion by adipose tissue." (PMID 39457712, 2024). "High levels of resistin have been observed in patients with hypertension, diabetes mellitus, and other atherosclerotic diseases, which are known risk factors for AIS." (PMID 39201031, 2024). "The RESISTIN pathway is a risk factor that makes periodontitis a precursor to type 2 diabetes mellitus." (PMID 38082425, 2023). "Herein, variables linked to resistin levels were those of comorbidities such as dyslipidemia and diabetes." (PMID 37355349, 2023). "Higher resistin levels were associated with increased aortic stiffness in patients with coronary artery disease, independently of age, diabetes mellitus, waist circumference, and CRP." (PMID 34202323, 2021). "Meanwhile, supplement with camel milk powder also significantly decreased serum content of resistin and lipocalin‐2, adipokines which was reported to be positively associated with diabetes." (PMID 34401094, 2021). "A higher intake of total and insoluble dietary fiber has been found to reduce the risk of diabetes by lowering the levels of inflammatory markers (such as fibrinogen activator inhibitor-1, resistin, C-reactive protein, and interleukin-6)." (PMID 34276373, 2021). "Much less is known about the determinants of resistin abundance in the fetal circulation and current reports regarding the association between cord blood resistin with diabetes during pregnancy are discordant." (PMID 32762639, 2020). "Increased resistin is likely a response of monocytes/macrophages to hyperglycemia and metabolic stresses associated with diabetes during pregnancy." (PMID 32762639, 2020). "Studies have linked inflammatory biomarkers to various diseases; resistin has been linked with diabetes, CRP with malaria and P-selectin with systemic inflammatory response syndrome." (PMID 31856765, 2019). "Higher resistin was associated with low physical activity (41.7% vs. 28.0%, p <0.01), coronary artery disease (20.0% vs. 13.6%, p<0.01), diabetes (26.1% vs. 21.9%, p<0.01), and dyslipidemia (62.5% vs. 57.1%, p<0.01)." (PMID 29662629, 2018). "Several studies suggest that resistin is associated with multiple inflammatory human diseases including diabetes and cardiovascular diseases." (PMID 29584687, 2018). "AAV9.Serca2a overexpression significantly reduced the expression of resistin and NFATc nuclear accumulation and reconciled diabetes-associated decrease in AMPKα phosphorylation." (PMID 30353146, 2018). "Normalization of diabetes-associated Ca2+ dyshomeostasis through myocardial-specific restoration of Serca2a expression in diabetic hearts controls resistin transcriptional activity via manipulation of NFATc." (PMID 30353146, 2018). "The results of our study showed that circulating resistin and visfatin were positively associated with the severity of atherosclerosis in elderly diabetes patients." (PMID 29848323, 2018). "A total of 422 patients with diabetes mellitus were recruited for this cross-sectional study to examine the association between resistin and intact FGF23." (PMID 30228288, 2018). "Several studies suggested that resistin is associated with multiple human diseases such as diabetes and cardiovascular diseases (e.g., arteriosclerosis and heart failure), but only few studies linked it to AD." (PMID 29584687, 2018).